CCR3 (C-C motif chemokine receptor 3)
Diseases named in the same sentence as CCR3 in open-access papers (continued):
Sharing a sentence is not in itself a finding about the gene and the disease.
colitis (8 papers, 2018 to 2025). Inflammation of the colon. "Untreated colitis mice and 50 μg TA-treated colitis mice exhibited significantly increased expression levels of CCR3 (p < 0.001 and p < 0.05, respectively) and SiglecF (p < 0.01 and p < 0.05, respectively) compared to those of the normal control group." (PMID 40333150, 2025). "On the contrary, an increase of CCR3+SSCHI eosinophils in the spleen was observed in IL-5 transgenic mice subjected to DSS-induced colitis." (PMID 35887133, 2022). "A prior study indicated that a cocktail of proinflammatory cytokines (GM-CSF, IFNγ, TNFɑ) boosts CCR3 expression in human peripheral blood neutrophils from healthy donors, and expression of these cytokines is highly induced during STm colitis and Ab pneumonia." (PMID 39193987, 2024). "In addition, the potential target gene for DHKNase-6 to shut colitis was screened as CCR3, which was ultimately most down-regulated after DHKNase-6 treatment." (PMID 39253100, 2024). "After 7 days of induced colitis, upregulation of the expression of 22 genes (Ccl2, Ccl3, Ccl4, Ccl5, Ccl6, Ccl7, Ccl12, Ccl17, Cxcl1, Cxcl2, Cxcl6, Cxcl9, Cxcl11, Ccr1, Ccr2, Ccr3, Ccr5, Ccr8, Cxcr2, Csf3, Osm, and Spp1) was observed in the CβG− group compared to the HβG- control group." (PMID 35163326, 2022). "Based on these findings and our observations of CCL28-dependent neutrophil accumulation in the gut during STm colitis and in the lung during Ab infection, we performed flow cytometry on single-cell suspensions from infected mouse tissues to evaluate surface expression of CCR3 and CCR10." (PMID 39193987, 2024). "CCL11 induces angiogenic responses via its receptor CCR3 in endothelial cells, and the relevance of CCL11 with respect to colitis has been demonstrated." (PMID 35805947, 2022). "Additionally, it examined the expression of CCR3, CCL11, IL-5Rα, and TLRs in TA-treated normal and colitis mice to evaluate the role of TA in enhancing eosinophil-mediated inflammation through the modulation of these receptors and ligands." (PMID 40333150, 2025). "Importantly, while, CCL24 was initially described as an eosinophil chemoattractant trough the receptor CCR3, experiments in rodents suggested it was not involved in eosinophil infiltration during colitis." (PMID 36311796, 2022). "A 16-gene signature (CARD12, CCL3, CCR3, CXCL1, F5, FAM210B, GADD45A, IL18bp, IL2RA, IL5, IL8, MMP9, PTGS2, SOCS3, TLR9 and UBE2C) was identified from 30 days post-tremelimumab initiation blood that discriminated patients developing grade 0–1 from grade 2–4 diarrhea/colitis." (PMID 30227886, 2018).
colon cancer (8 papers, 2011 to 2021). "Here, the CCL7/CCR3 signaling axis has been described to promote colon cancer metastasis in a ERK-JNK-dependent manner." (PMID 31963450, 2020). "This study is the first one focusing on metastasis via CCL7/CCR3 crosstalk and related signaling pathways in colon cancer." (PMID 27167205, 2016). "Similar to these results, we also found that CCL7/CCR3 crosstalk induced EMT process in colon cancer cells." (PMID 27167205, 2016). "Third, we observed that CCL7 activated ERK and JNK signaling in MAPK pathways through CCR3 in colon cancer cells." (PMID 27167205, 2016). "Taken together, our data indicate that CCL7 can significantly stimulate CCR3 expression in colon cancer cells." (PMID 27167205, 2016). "Differences in the statistical significance of CCR3 in the case of rectal cancer and its absence in the case of colon cancer may be related to the differences in the biology of these two neoplasms." (PMID 34204490, 2021). "CCL7 also promoted colon cancer cell metastasis via CCR3 through both the ERK and JNK pathways." (PMID 34206004, 2021). "Also, the interaction between CCL7 and CCR3 has been shown to promote colon cancer cell metastasis via ERK-JNK signaling." (PMID 31419632, 2019). "In conclusion, our results imply that CCR3- correlated ERK-JNK activation may be a molecular link in the induction of metastasis by CCL7 in colon cancer cells." (PMID 27167205, 2016). "These novel finding strongly suggest that suppressing oncogenic communication between CCL7 and CCR3 may be a potential therapeutic strategy for preventing human colon cancer metastasis." (PMID 27167205, 2016). "To further determine which receptor on colon cancer cells is responsible for the paracrine effect of CCL5 secreted by hMSCs, we examined the mRNA expression levels of ccr1, ccr3, and ccr5 in SW1116." (PMID 28542126, 2017). "Evidence of such mechanistic interplay between CCL7/CCR3 and ERK–JNK cascade provides important insights into cell invasion and migration in colon cancer." (PMID 27167205, 2016). "These compelling results reveal that CCR3 is a major activator of CCL7 induced cell invasion and migration, the major characteristics of EMT in colon cancer cells." (PMID 27167205, 2016). "While CCL5 can bind to CCR1, CCR3, and CCR5, we revealed that the paracrine CCL5-induced cell migration in colon cancer cells was mainly mediated by CCR1, given that CCR1 antagonist completely abolished the increased migration in colon cancer cells in response to CCL5." (PMID 28542126, 2017).
Sepsis (8 papers, 2016 to 2024). Sepsis is defined as life-threatening organ dysfunction caused by a dysregulated host response to infection. "The PTGDR2, a chemoattractant receptor molecule (CRTH2), and CCR3, are reported to be expressed on Th2 cells and eosinophils, and their co-expression was linked to Th2 response in sepsis inflammatory response." (PMID 36005179, 2022). "CCR3, PTGDR2 (alias CRTH2), and FCER1A are associated with allergic processes and have been described in sepsis and bacterial meningitis." (PMID 30463588, 2018). "Once the increased level of eotaxin-1/CCL11 has been proven to be a culprit of sepsis-induced myocardial injury, CCR3 agonists may provide a novel targeted therapy." (PMID 32147601, 2020). "In the genes differentially expressed between SRS groups, there was evidence of enrichment for eQTL (χ2 p<0·0001), including for genes previously implicated in the pathogenesis of sepsis and its treatment, such as IL18RAP, CCR1, CCR3, and SIRT1 (appendix 1 pp 17–18 and appendix 2)." (PMID 26917434, 2016). "We established a prognostic model consisting of four sepsis-related genes: KRT20, PAEP, CCR3, and ANLN." (PMID 39421149, 2024). "As shown in these figures, the expression levels of RETN, S100A12, IL18R1, and KL were higher in the sepsis group, while that of GZMB, HLA-DPA1, CD3E, IL2RB, CD3G, and CCR3 were higher in the normal group (p < 0.05)." (PMID 38124071, 2023). "Our findings showed that the expression of RETN, S100A12, IL18R1, and KL was higher in the sepsis group, while the expression of GZMB, HLA-DPA1, CD3E, IL2RB, CD3G, and CCR3 was higher in the control group." (PMID 38124071, 2023). "We also detected sepsis eQTL involving the most significant disease SNP for Behcet's disease, which we find modulates expression of the chemokine receptor genes CCR1 and CCR3, which are upregulated and downregulated, respectively, in patients with SRS1." (PMID 26917434, 2016).
breast tumor (7 papers, 2016 to 2025). "CCL5 mediates breast tumor progression and recurrence by interacting with the CCR3 axis, recruiting macrophages and regulating the CD4+/CD8+, CCR5+/CD4+ or Treg/CCR5+ cell ratios." (PMID 37051596, 2023). "CCR3 and CX3CR1 were differentially expressed between Black versus White, and CCR6, CCRL2, and CXCR4 between Asian versus White breast tumors." (PMID 35754051, 2022). "Conversely, of the 511 CSRs overexpressed in breast tumours relative to healthy breast tissue, 72 were significantly underexpressed when compared to non-breast healthy tissues, including well-established drug targets like FGFR3, CD48, and CCR3." (PMID 38306344, 2024).
colorectal cancer (7 papers, 2011 to 2026). A primary or metastatic malignant neoplasm that affects the colon or rectum. "In addition, differential expression of genes linked to intestinal bowel disease (i.e. Ccr3, Ccl11 and Tnfr) and colorectal cancer development (i.e. Wt1 and Mmp25) was observed between males and females." (PMID 25243059, 2014). "We noticed that the CCR3 area under the ROC curve (0.683) in the total group of colorectal cancer was the highest from all the tested parameters but lower than the AUC for CEA and CRP." (PMID 34204490, 2021). "Similar to our results, there are reports showing that CCL7 interactions with CCR3 promote the metastasis of neurofibroma and colorectal cancer." (PMID 34206004, 2021). "Moreover, CCL11 may also regulate eosinophil migration in the tumor microenvironment through its interaction with CCR3, and its significant role has been confirmed in colorectal cancer, Hodgkin lymphoma, and oral squamous cell carcinoma." (PMID 38459592, 2024). "Studies have shown that Eotaxin-1 and its receptors are significantly upregulated in colorectal cancer, especially CCL11 and CCR3 (the receptor for CCL11)." (PMID 39399504, 2024).
hepatocellular carcinoma (7 papers, 2022 to 2026). A malignant tumor that arises from hepatocytes. "In liver biopsies from patients with nonalcoholic steatohepatitis (NASH) and hepatocellular carcinoma, both CCR3 and CCL24 were found to be hyperexpressed, and high CCR3 expression in hepatic fibroblasts was demonstrated in both liver diseases." (PMID 37345655, 2023). "In liver diseases such as non-alcoholic steatohepatitis (NASH) and hepatocellular carcinoma (HCC), CCL24 and CCR3 are upregulated, and CCL24 blockade with the neutralizing antibody CM-101 reduced liver damage and fibrosis in preclinical models." (PMID 38334601, 2024). "CCL5 activity is mediated through its binding to CCR5, CCR3, and CCR1 but only CCR1 is expressed in hepatocellular carcinoma cells (HCC)." (PMID 35399952, 2022). "Three specific receptors of CCL5 include CCR1, CCR3, and CCR5.We also found that CAF-derived CCL5 or exogenous hCCL5 could obviously enhanced the expression of CCR3 and CCR5 in hepatocellular carcinoma cells." (PMID 35589690, 2022).
lymphoma (7 papers, 2016 to 2025). A malignant (clonal) proliferation of B- lymphocytes or T- lymphocytes which involves the lymph nodes, bone marrow and/or extranodal sites. "Although CCR3, CCR6, CCR8, PITPNM3, and GPER1 encode receptors of CCL18, only CCR6 was expressed in the lymphoma cells." (PMID 39894788, 2025). "In POD24‐FLs, weak CXCR3 and CXCR4 expression was found in 13.33% and 40% of lymphoma cells, with moderate CCR3 and CXCR5, and strong CCR7 in 50%, 70%, and 50%, respectively." (PMID 40896244, 2025). "In non‐POD24‐FLs, weak CCR3, CXCR3, and CXCR4 expression was observed in 50%, 11.8%, and 40% of lymphoma cells, respectively, while moderate CXCR5 and strong CCR7 expression was detected in 68.3% and 50%." (PMID 40896244, 2025). "However, CCR3/CD193, a receptor for CCL26 and other ligands, is not expressed on lymphoma cells in MF or SS." (PMID 29915722, 2018).
atopic dermatitis (6 papers, 2006 to 2025). "Eotaxin (CCL11), a Type-2 chemokine, is a potent chemoattractant and activator of CC chemokine receptor-3 (CCR3)-expressing eosinophils that accumulate in high numbers in the lungs of asthmatic patients as well as in the lesional skin from atopic dermatitis patients." (PMID 29933387, 2018).
influenza (6 papers, 2009 to 2024). An acute viral infection of the respiratory tract, occurring in isolated cases, in epidemics, or in pandemics; it is caused by serologically different strains of viruses (influenzaviruses) designated A, B, and C, has a 3-day incubation period, and usually lasts for 3 to 10 days. "In addition Th2-type cytokines, such as IL-4 and IL-13, and markers of eosinophil chemotaxis, such as CCL11 and CCR3, were increased in OVA-sensitized mice exposed to DEP prior to infection with influenza." (PMID 19682371, 2009). "In addition to observing increased numbers of CCR3-expressing eosinophils, our data also showed that exposure to DEP prior to infection with influenza increases the expression of CCL11." (PMID 19682371, 2009). "Only animals that were exposed to DEP prior to infection with influenza showed significant changes in the number of BALF/lung eosinophils, CCL11, CCR3, or TH2 cytokines, suggesting that exposure to DEP primed the animals for virus-induced exacerbation of allergic inflammation." (PMID 19682371, 2009). "Interestingly neither exposure to DEP or infection with influenza alone had any significant effect on the expression of CCL11 or CCR3 in OVA-sensitized mice." (PMID 19682371, 2009). "Lung-recruited neutrophils induced CCR1, CCR2, CCR3, CCR5, CXCR1, CXCR3, CXCR4, which were absent or marginally induced in peripheral blood neutrophils from influenza-infected mice." (PMID 31041196, 2019).
narcolepsy (6 papers, 2017 to 2024). A sleep disorder characterized by a tendency for excessive sleepiness during the day which occurs even after adequate sleep in the nighttime. "Chemokine receptor 3 (CCR3) has been identified as a susceptibility gene linked to narcolepsy, with studies indicating a diminished expression level in the peripheral blood of individuals diagnosed with this condition." (PMID 39595997, 2024). "In conclusion, we propose that impaired function of CCR3 causes fragmented sleep that can contribute to vulnerability to developing narcolepsy in an inflammatory context induced by environmental triggers." (PMID 29186205, 2017). "We previously reported that chemokine (C-C motif) receptor 3 (CCR3) is a susceptibility gene associated with narcolepsy and that its mRNA expression levels in peripheral blood are lower in narcolepsy patients." (PMID 29186205, 2017). "We previously reported chemokine (C-C motif) receptor 3 (CCR3) as a novel susceptibility gene for narcolepsy." (PMID 29186205, 2017). "Shiftwork may negatively affect genes and factors involved in sleep disorders such that a SNP marker and chemokine (C-C motif) receptor 3 (CCR3) susceptibility gene associated with narcolepsy, MEIS1 locus, and neuronal nitric oxide synthase (NOS1) and BTBD9 associated with RLS." (PMID 29607311, 2018). "To investigate the role of CCR3 in the development of narcolepsy, we examined sleep-wake patterns in Ccr3 KO mice." (PMID 29186205, 2017). "A recent publication also reported reduced levels of the chemokine receptors CCR1 and CCR3 in peripheral blood samples of patients with narcolepsy." (PMID 28912686, 2017). "Reduced levels of microglia/macrophage-derived CCR1 and CCR3 are measured in peripheral blood samples from narcolepsy patients." (PMID 28912686, 2017). "To understand the role of CCR3 in the development of narcolepsy, we investigated sleep-wake patterns of Ccr3 knockout (KO) mice." (PMID 29186205, 2017). "The phenotypes of Ccr3 KO mice were different from those of Hcrt deficient mice; however, the fragmented sleep-wake patterns of Ccr3 KO mice in the light phase are suggestive of fragmented nocturnal sleep in human narcolepsy." (PMID 29186205, 2017). "An investigation using other immune stimulators such as viral single/double-stranded DNA/RNA is essential for understanding the interactive contribution of CCR3 and environmental factors to the narcolepsy development." (PMID 29186205, 2017). "The LPS-induced dysfunction of CCR3 in these mice provides a valuable model for investigating the immune-mediated degeneration of HCRT neurons triggered by environmental factors, thereby contributing to a deeper understanding of the immune pathogenesis associated with narcolepsy." (PMID 39595997, 2024). "Given that AS03 adjuvanted vaccinations increase the risk for narcolepsy, we speculate that elevated chemokines may mediate the immune response that results in the increased risk of narcolepsy; meanwhile, the CCL5 receptor, CCR3, plays a protective role in Hcrt neuronal survival." (PMID 29186205, 2017).
ovarian carcinoma (6 papers, 2015 to 2021). A malignant neoplasm originating from the surface ovarian epithelium. "CC chemokine receptor 3 (CCR3) was highly expressed in human ovarian cancer cells, and a specific inhibitor of this receptor reduced the OC-MQ-CM-induced invasion." (PMID 34206004, 2021). "It has been reported that CCL5-induced invasion of ovarian cancer stem-like cells is mediated by CCR1 and CCR3, and CCR3, along with CCR2 and CCR5, are associated with CCL11-stimulated proliferation, migration, and invasion of ovarian cancer cells." (PMID 34206004, 2021). "CCL7 from OC-MQs, which mimic TAMs, promoted ovarian cancer cell migration and invasion through the CCR3-ERK pathway." (PMID 34206004, 2021). "In the current study, we demonstrated that CCL7 derived from macrophages stimulated the invasion and migration of ovarian cancer cells via CCR3." (PMID 34206004, 2021). "Consequently, our results demonstrated the pro-malignant role of the CCL7/CCR3 axis and suggested that targeting this axis could be an effective method to inhibit the metastatic spread of ovarian cancer cells by regulating the tumor microenvironment." (PMID 34206004, 2021). "However, CCR3 is expressed in human ovarian cancer and might, therefore, be another important receptor to promote metastasis in patients." (PMID 32963283, 2020). "Together, these data suggest that CCR3 in human ovarian cancer cells can be stimulated by CCL7 from TAMs, as well as CCL5 and CCL11, and can play a critical role in ovarian cancer metastasis." (PMID 34206004, 2021). "In CD133+ ovarian carcinoma stem-like cells selected from ovarian carcinoma cell lines and primary tissues, CCL5 and its receptors CCR5, CCR1, and CCR3, were up-regulated." (PMID 32630699, 2020). "To investigate this, we collected cancer tissues, corresponding metastatic tissues, and paracancerous tissues from 20 patients with epithelial ovarian cancer and determined the expression levels of CCL5 and its receptors (CCR1, CCR3, and CCR5)." (PMID 25788271, 2015). "Moreover, OC-MQ-stimulated ovarian cancer cell invasion was markedly attenuated by SB297006, a specific CCR3 inhibitor." (PMID 34206004, 2021). "We identified basophils (CCR3-PEhighSSClow, 0.64% ± 0.06 of white blood cells (WBC), range 0.02–2.3%) in unfractionated whole blood samples from 52 of a cohort of 53 patients with ovarian cancer." (PMID 32645919, 2020).
rheumatoid arthritis (6 papers, 2018 to 2025). A chronic, systemic autoimmune disorder characterized by inflammation in the synovial membranes and articular surfaces. "Previous studies have also demonstrated that CCR3 is highly expressed in infiltrated synovial neutrophils of rheumatoid arthritis patients." (PMID 30972099, 2019). "With the exception of the CCR3 gene for rheumatoid arthritis, none of the TG-affected genes were associated with these diseases on the basis of the two-sample MR approach." (PMID 36725846, 2023). "It has been reported that CCR3 expression was increased under rheumatoid arthritis conditions, and it mediated eotaxin-1 induced matrix metalloproteinase (MMP)-9 upregulation in fibroblast-like synoviocyte which may further result in articular damage." (PMID 30972099, 2019). "In rheumatoid arthritis (RA), fibroblast-like synoviocytes (FLS) are pathogenic effectors and a major CCR3-expressing cell." (PMID 33846499, 2021).